SIRT1 (sirtuin 1)
Diseases named in the same sentence as SIRT1 in open-access papers (continued):
Sharing a sentence is not in itself a finding about the gene and the disease.
cardiac hypertrophy (continued). "On the other hand, pressure overload co‐up‐regulate SIRT1 and PPAR‐α in the heart, which coordinately suppress genes that are regulated by ERRs, thereby leading to the development of cardiac hypertrophy and heart failure." (PMID 28296029, 2017). "Studies from other laboratories showed that increased level of intracellular NAD+ enhanced the activities of SIRT1 and SIRT3 33, which in turn, suppressed cardiac hypertrophy through the activation of Foxo3a‐dependent antioxidant defence mechanism." (PMID 28296029, 2017). "To date, three family members—SIRT1, SIRT3, and SIRT7—havebeen shown to block stress-induced cardiac hypertrophy by impinging upon ROSgeneration." (PMID 20375467, 2010). "While our study delineates the central role of the AMPK/SIRT1 axis, our KEGG enrichment analysis also suggests the potential involvement of other downstream pathways such as mTOR signaling and autophagy—key regulators of cardiac hypertrophy." (PMID 41010549, 2025). "Ginkgolide B enhances autophagy via the SIRT1/FOXO1 signaling pathway, inhibits Ang II-induced myocardial hypertrophy, and may potentially serve as a therapeutic modality for pathological cardiac hypertrophy." (PMID 37754811, 2023). "SIRT1, SIRT3, and SIRT6 might protect against cardiac hypertrophy and fibrosis by affecting important biological processes and regulating downstream signaling pathways, such as autophagy and TGF-β/Smad3 pathways." (PMID 36581622, 2022). "In addition, SIRT1 is also involved in cardiac hypertrophy, and deacetylated protein kinase C-δ (PKC-δ) can improve cardiac hypertrophy." (PMID 35855865, 2022). "Fisetin improved the myocardial function by alleviating cardiac dysfunction, ameliorating myocardial fibrosis, mitigating cardiac hypertrophy in DOX-induced rats, and increasing the expressions of SIRT1/Nrf2 pathway genes, HO-1 and FTH1, in rats and H9c2 cells." (PMID 35273493, 2021). "Mice lacking SIRT1 have a reduced physiological cardiac hypertrophy after exercise, indicating the importance of the AKT/SIRT1 pathway for a healthy heart." (PMID 33806509, 2021). "SIRT1 is able to activate AKT, which has two potential downstream effects: it can promote physiological cardiac hypertrophy, or it can antagonize pathological cardiac hypertrophy." (PMID 33806509, 2021). "Our study also shows that cardiac hypertrophy in response to pressure overload is possible in the absence of SIRT1 even though the hypertrophic role of SIRT1 has been documented." (PMID 31658614, 2019). "Other authors have suggested that ALA partially attenuates cardiac hypertrophy via inhibition of PPAR2 and subsequent activation of Sirt1 and have proposed that it may have a potential cardio-protective role." (PMID 27690014, 2016). "It has been shown that knockdown of SIRT1 increases the level of crotonylation of SERCA2a to decrease its activity, which in turn affects the expression of proteins in the PPAR pathway, leading to changes in energy metabolism and alterations in physiological states such as cardiac hypertrophy." (PMID 40710369, 2025). "Sirtuin 1 (SIRT1), a NAD+ dependent deacetylase, plays a key role in cardiovascular health and pathology by regulating fundamental processes such as endothelial function, oxidative stress, inflammation, senescence, metabolism, cardiac hypertrophy, and heart failure." (PMID 41567643, 2025). "Furthermore, deletion of SIRT1 restricted the anti-oxidative and anti-apoptotic activities of FGF20 on pathological cardiac hypertrophy; this finding is consistent with our hypothesis." (PMID 35351862, 2022). "SIRT1 overexpression at high levels (more than 12 times above normal) has negative effects on cardiac function, but low to moderate overexpression of SIRT1 in transgenic mice prevents the age-dependent development of cardiac hypertrophy and fibrosis." (PMID 35629426, 2022).
cardiac hypertrophy (continued). "In our present study, the reduction on SIRT1 after ISO administration could not be restored by NaHS, suggesting that SIRT1 is not involved in the protective effect by H2S on ISO-induced myocardial hypertrophy." (PMID 30647820, 2018).
lung carcinoma (134 papers, 2011 to 2025). "Our current work reveals a novel molecular mechanism underlying SIRT1 ISGylation for the regulation of tumor progression and the response to DNA-damaging chemotherapeutics in lung cancer, as depicted in the summary schematic." (PMID 38443596, 2024). "In a recent study, low SIRT1 expression levels were associated with poor prognosis in lung cancer patients." (PMID 32489467, 2020). "A previous study showed that SIRT1 expression is negatively associated with chemotherapy response and the prognosis of lung cancer." (PMID 29312612, 2017). "Previous studies have shown that the expression of SIRT1 is associated with poor prognosis in lung cancer." (PMID 29312612, 2017). "Downregulation of SIRT1 significantly attenuates the TGF-β1-induced EMT-associated migration and invasion by lung cancer cells, indicating that SIRT1 enhances cancer cell motility during EMT, and therefore represents a novel target for cancer therapies." (PMID 27528025, 2016). "Taking these data together, we conclude that upregulated NER capacity in preconditioned lung cancer cells is caused partly by an increased level of SIRT1, which modulates XPA sensitivity to DNA damage." (PMID 26317794, 2015). "SIRT1 suppresses lung adenocarcinomas driven by K-Ras, indicating that reduced SIRT1 may also increase the risk of lung cancer." (PMID 40554265, 2025). "Overexpression or hyperactivation of SIRT1 is closely associated with poor prognosis, metastasis, chemoresistance, and oxidative stress resistance in multiple cancer types, including ovarian, liver, breast, and lung cancers." (PMID 41008982, 2025). "Subsequently, using the K‐M plotter, we investigated the relationship between the expression of SIRTs and prognostic survival rate in lung cancer patients and found that the high expression of SIRT1, SIRT3 and SIRT4 was associated with better prognosis, respectively." (PMID 39501597, 2024). "SIRT1 overexpression is associated with poor prognosis in patients with lung cancer." (PMID 31956359, 2020). "Moreover, shikonin causes apoptosis in some lung cancer cell lines via the FOXO3a/EGR1/SIRT1 signaling pathway activation." (PMID 31956359, 2020). "In particular, SIRT1 has been associated with poor prognosis in lung cancer patients." (PMID 29348853, 2017). "Notably, SIRT1-deficient lung cancer-derived ECs overexpressing N1IC displayed a markedly enhanced level of HEY1 and HEY2 activity." (PMID 23028940, 2012). "Furthermore, the enhanced Notch responsiveness to DLL4 of the SIRT1-deficient lung cancer-derived ECs was abrogated by the addition of the γ-secretase inhibitor DAPT." (PMID 23028940, 2012). "Clinical data from lung cancer patients indicated that higher expression of SIRT1 and OXPHOS-associated proteins correlated with tumor recurrence and poor survival, supporting that OXPHOS inhibitors could be a part of a combination therapy for better clinical outcome in these patients." (PMID 36497394, 2022). "Therefore, we examined whether SIRT1 expression was associated with the survival rate of lung cancer patients." (PMID 32489467, 2020). "For example, miR-133a-3p, found in lung cancer serum exosomes, silences specific proteins such as Sirtuin 1 (SIRT1) through targeted mechanisms." (PMID 40028322, 2025). "On the other hand, quercetin-inhibition of autophagy contributes to apoptosis in A549 and H1299 lung cancer cells, which involves the SIRT1/AMPK signaling pathway." (PMID 39863836, 2025). "Quercetin activates the AMPK/SIRT1 axis to improve amyotrophic lateral sclerosis and contributes to apoptosis in A549 and H1299 lung cancer cells." (PMID 40510834, 2025). "Taken together, our results suggest that SIRT1 ISGylation promotes lung cancer progression and limits sensitivity to doxorubicin." (PMID 38443596, 2024).
lung carcinoma (continued). "For example, QCT promoted the apoptosis and pyroptosis of lung cancer cells through the SIRT1/AMPK signal pathway." (PMID 38526326, 2024). "ZMIZ2 promotes the malignant phenotype of lung cancer by regulating Wnt/Hippo pathways through SIRT1, providing an experimental basis for discovering novel biomarkers and developing tumor-targeted drugs." (PMID 39266996, 2024). "SIRT1 deacetylates and enhances KRASMut activity in lung cancer, and inhibiting SIRT1 or activating p300, which acetylates KRASMut, sensitizes tumors to cisplatin and erlotinib, offering a potential combination therapy for KRASMut lung cancer." (PMID 39403142, 2024). "The interaction between ZMIZ2 and SIRT1 results in the activation of the Wnt pathway and inhibition of the Hippo pathway, thereby promoting the biological phenotypes of lung cancer, including cell proliferation, invasion, and metastasis." (PMID 39266996, 2024). "Among DNA-damaging agents, SIRT1 inhibitor (EX527) in combination with erlotinib has shown combined anti-lung cancer effects by reducing cancer cell proliferation and enhancing DNA damage." (PMID 39479446, 2024). "In lung cancer, miR-124 and miR-142 downregulation of SIRT1 suppresses supportive autophagy, enhancing cisplatin sensitivity and promoting apoptosis." (PMID 39403142, 2024). "Intriguingly, SIRT1 has been reported to play an important role in lung cancer development and chemoresistance." (PMID 38443596, 2024). "To verify the effect of cambinol treatment was due to SIRT1 activity we next knocked down the gene in lung cancer cells." (PMID 39100092, 2024). "SIRT1 ISGylation promotes not only tumorigenesis but also chemoresistance in vivo and in vitro models of lung cancer." (PMID 38443596, 2024). "To establish the functional role of SIRT1 ISGylation in lung cancer progression and the response to DNA-damaging chemotherapeutics in vivo, we engrafted SIRT1 KO, SIRT1 WT-complemented and SIRT1 KR-complemented cells into BALB/c nude mice." (PMID 38443596, 2024). "Quercetin, a natural compound, induces apoptosis and toxic autophagy in lung cancer, where increased SIRT1 levels upregulate AMPK, leading to autophagy-mediated apoptosis." (PMID 39403142, 2024). "To determine the potential effects of SIRT1 ISGylation on lung cancer progression and therapeutic efficacy, we first examined the impact of SIRT1 ISGylation on lung cancer cell proliferation." (PMID 38443596, 2024). "SIRT1 ISGylation promotes lung cancer progression and reduces the sensitivity of lung cancer cells to DNA damage-based therapies." (PMID 39403142, 2024). "Higher expression of SIRT1 was found in seven of the lung cancer tissues (63.6%) than in the paired adjacent normal tissues." (PMID 38443596, 2024). "The downregulation of SIRT1/2 can induce protective autophagy in lung cancer by increasing the acetylation of HSPA5, which in turn elevates ATF4 and DDIT4 levels, suppressing mTOR and promoting pro-survival autophagy." (PMID 39403142, 2024). "Quercetin activation of SIRT1 to induce autophagy in A549 and H1299 human lung cancer cells and contributes to lung cancer cell apoptosis." (PMID 39479446, 2024). "Taken together, our findings provide a mechanistic understanding of the regulatory effect of SIRT1 ISGylation on tumor progression and therapeutic efficacy in lung cancer." (PMID 38443596, 2024). "Doxorubicin induced ISGylation of endogenous SIRT1 in both A549 and H23 cells derived from lung cancer, in which it was robustly able to induce ISG15 expression and protein ISGylation conjugates formation." (PMID 38443596, 2024). "Celecoxib inhibited EMT and lung cancer migration and invasion through silent mating type information regulation 2 homolog (SIRT-1) down-regulation." (PMID 38170401, 2024). "Sirt1 can acetylate or deacetylate and regulate multiple pathways in lung cancer, like acetylation of AMP, AKT, PPAR γ, and more." (PMID 38020163, 2023).
lung carcinoma (continued). "Collectively, these data indicate that SIRT1 K/D can sensitize KrasMut lung cancer cells to chemotherapy or EGFR TKI treatment." (PMID 37779142, 2023). "Therefore, we thought that SIRT1 K/D may result in different secondary changes to KRASMut downstream signaling and/or act through a feedback mechanism to compensate for the loss of oncogenic KRASMut in lung cancer." (PMID 37779142, 2023). "The intensification of SIRT1’s deacetylating activity in lung cancer cell lines A549 and H1435 leads to the deacetylation of the FOXO3 (forkhead box O3) factor and its increased susceptibility to ubiquitination and proteasomal degradation." (PMID 37762053, 2023). "In contrast, there are research reports that emphasize the importance of Sirt6 in regulating the random acetylation of Sirt1 with respect to lung cancer." (PMID 38020163, 2023). "In monoclonal-treated mice with lung cancer, the tumor area and weight were significantly reduced, while T-cell counts, oxidative stress, apoptosis, autophagy, activated p65, and sirtuin-1 markers were increased." (PMID 37357527, 2023). "One consistent attribute of lung cancer cells is the overexpression of sirtuin 1 and 2 (SIRT1/2) proteins compared to normal human bronchial epithelial cells where enhanced SIRT1/2 expression has been correlated with a poor prognosis in NSCLC patients." (PMID 37397370, 2023). "Here, we demonstrated that the mRNA and protein levels of the class III histone deacetylase SIRT1 were upregulated by the KRASMut-Raf-MEK-c-Myc axis in KRASMut lung cancer cells and in lung tumors of a mouse model with spontaneous KrasG12D expression." (PMID 37779142, 2023). "Our data reveal a novel pathway critical for the regulation of KRASMut lung cancer progression and provide important evidence for the potential application of SIRT1 inhibitors and p300 activators for the combination treatment of KRASMut lung cancer patients." (PMID 37779142, 2023). "An analysis of resveratrol and IR effects on A549 and H460 lung cancer cells showed that SIRT1 expression was negatively correlated with radiosensitivity in lung cancer cell lines." (PMID 36142554, 2022). "Findings to date indicate that SIRT1 in lung cancer is indirectly regulated by miRNA-21 but the precise mechanisms of action remain to be established." (PMID 35441676, 2022). "Among them, SIRT1 was highly expressed in chemotherapy-resistant lung cancer cells and promoted chemotherapy resistance of lung cancer cells." (PMID 34696659, 2022). "Taken together, miR-326 represses SIRT1 through impeding HIF1α expression, thus hindering chemotherapy resistance in lung cancer." (PMID 34696659, 2022). "JH-T4 inhibits SIRT-1, -2, and -3 and it has an antiproliferative effect on breast, colorectal, and lung cancer cells." (PMID 36080416, 2022). "Compounds 27 and 30, discovered by Mellini and colleagues upon synthesis of a compound library of 30 pseudopeptides, were reported to inhibit SIRT-1, -2, and -3 and they are able to arrest cell growth in breast and lung cancer cells." (PMID 36080416, 2022). "Celecoxib was able to inhibit TGF-β stromal expression in A549 lung cancer cells, preventing cancer cells migration and invasion via SIRT1 downregulation." (PMID 33922284, 2021). "The overexpression of SIRT1 promotes the progression of various solid tumors such as lung cancer, breast cancer, ovarian cancer, gastric cancer, colon cancer, and esophageal squamous cell carcinoma, and is an indicator of poor prognosis." (PMID 34381712, 2021).
lung carcinoma (continued). "Second, Guan, Rao & Chen (2017) have found that miR-30a suppresses lung cancer progression by targeting SIRT1." (PMID 34178448, 2021). "Western blot revealed the expression of SIRT1 in all lung cancer cell lines, but the treatment of cells with RESV and/or PRI-2191 did not significantly influence the level of expression." (PMID 33652978, 2021). "In contrast, in lung cancer cell lines the apoptosis induction by SHI has been attributed to the FOXO3a/EGR1/SIRT1 pathway." (PMID 33672520, 2021). "Both genetic and chemical inhibition of SIRT1 can reverse chemoresistance in lung cancer cells by enhancing DNA damage and activating apoptosis, concomitant with XRCC1 degradation." (PMID 34381712, 2021). "RES, the agonist of SIRT1, can antagonize the transformation of SIRT1 caused by hypoxia, thus inhibiting EMT in lung cancer cells." (PMID 33937049, 2021). "The ATF4-DDIT4-mTORC1 axis will inhibit the cancer therapy by activation of the autophagy signal pathway, and the combinatorial treatment with SIRT1/2 inhibitors and pharmacological autophagy inhibitors was an effective therapeutic strategy in lung cancer." (PMID 34007269, 2021). "SIRT1 is involved in BaP-induced transformation associated with TNF-α-β-catenin axis activation and is a potential therapeutic target for lung cancer." (PMID 31956359, 2020). "We analyzed the two groups through the Kaplan-Meier plotter program about lung cancer to see the impact of SIRT1 expression on relapse-free survival." (PMID 32489467, 2020). "Recent data have shown low expression levels of SIRT1 in human colon cancer, lung cancer, and glioblastoma." (PMID 32051395, 2020). "Next, we assessed mRNA/protein expression of SIRT-1, a major deacetylase believed to play a pro-tumorigenic role in lung cancer and shown to be required for CAV-1 expression." (PMID 32733649, 2020). "By contrast to the tumor-suppressing role of SIRT2/4, the roles of SIRT1/6/7 and mitochondrial SIRT3/5 are strongly associated with drug resistance in lung cancer 119, 120, 124, 135, 142, 144, 146, 150-154." (PMID 31956359, 2020). "The cell viability, invasion, and metastasis of lung cancer cell A549 and H1299 were detected with the treatment of baicalin by activating the SIRT1/AMPK signaling pathway." (PMID 33585556, 2020). "We next analyzed the effect of SIRT1 inhibition by chemical inhibitors on chemoresistance of lung cancer cells." (PMID 31043584, 2019). "Here, we describes SIRT1 confers chemoresistance to lung cancer cells by deacetylating and stabilizing XRCC1." (PMID 31043584, 2019). "Our study also indicates that downregulation of SIRT1 by PPD is correlated with EMT in lung cancer cells." (PMID 31133857, 2019). "SIRT1 repression increases cellular levels of acetylated FOXO1 that transcriptionally activates apoptotic signaling in the lung cancer cells." (PMID 31689236, 2019). "SIRT1 is upregulated in chemoresistant lung cancer cells, genetic knockdown or chemical inhibition of SIRT1 reversed chemoresistance by enhancing DNA damage and apoptosis activation, accompanied with XRCC1 degradation." (PMID 31043584, 2019). "In present study, we found that SIRT1 expression was upregulated in chemotherapeutic resistant lung cancer cells." (PMID 31043584, 2019). "In the present study, we found that SIRT1 is overexpressed to promote chemoresistance in lung cancer." (PMID 31043584, 2019).